ANKRD24 (ankyrin repeat domain 24)
Description:
Component of the stereocilia rootlet in hair cells of inner ear. Bridges the apical plasma membrane with the lower rootlet and maintains normal distribution of TRIOBP, thereby reinforcing stereocilia insertion points and organizing rootlets for hearing with long-term resilience.
Synonyms: KIAA1981
Tractability: Antibody: UniProt places it where antibodies can reach, with medium confidence; its Gene Ontology location is reachable by antibodies, with medium confidence.
Gene: Protein-coding gene on chromosome 19 (4,182,630 to 4,224,818, forward strand). Ensembl gene ENSG00000089847.
Subcellular location: Cell membrane; Cell projection, stereocilium
Subcellular location (Human Protein Atlas): Cytosol; Microtubules
Gene Ontology:
Molecular function: actin binding
Biological process: auditory receptor cell stereocilium organization; sensory perception of sound
Cellular component: plasma membrane; stereocilium
Genetic constraint (gnomAD): Loss-of-function variants: 109 observed, 101.83 expected, observed/expected ratio (o/e) 1.07, 90% interval 0.92 to 1.25. The synonymous counts are far from expectation, so gnomAD's model fits this gene poorly and the ratio says little. Missense variants: 1,648 observed, 1,367.8 expected, observed/expected ratio (o/e) 1.2, 90% interval 1.16 to 1.25. Synonymous variants: 743 observed, 558.78 expected, observed/expected ratio (o/e) 1.33, 90% interval 1.25 to 1.41.
Homologues: Orthologues: chimpanzee ANKRD24 (96% identical), macaque ANKRD24 (94% identical), pig ANKRD24 (78% identical), dog ANKRD24 (77% identical), mouse Ankrd24 (55% identical), rat Ankrd24 (53% identical), zebrafish ankrd24 (33% identical), tropical clawed frog ankrd24 (27% identical). Paralogues in human: UACA (24% identical), ASB2 (10% identical).
Diseases named in the same sentence as ANKRD24 in open-access papers:
ANKRD24 is named in the same sentence as 5 diseases in open-access papers, as found by Europe PMC text mining. Sharing a sentence is not in itself a finding about the gene and the disease. The quoted sentences say what the papers report.
deafness (1 paper, 2022). An inherited or acquired condition characterized by the complete loss of the ability to hear from one or both ears. "Loss of ANKRD24 leads to fragile stereocilia; accordingly, Ankrd24KO/KO mice have high-frequency hearing loss that progresses to near-complete deafness by 6 mo of age." (PMID 35175278, 2022).
gastritis (1 paper, 2025). Inflammation of the stomach. "Furthermore, in the gastric mucosa of the patients with H. pylori-infected gastritis, USP15, ZNF451, TGFB1, and CCNT were identified as participants in the TGF-β signaling pathway, while FYB, HLA-DRB1, ANKRD24, and TMEM35 were implicated in T lymphocyte differentiation and immune response processes." (PMID 41035878, 2025).
tumor (1 paper, 2023). "In contrast, we have not found sufficient bibliographic evidence to support the role of ANKRD24 and MROH2A in the tumor process." (PMID 37175550, 2023).
ANKRD24 also shares sentences with these, for which no sentence is quoted: cancer (1 paper); Spinocerebellar Ataxia 17 (1).